IL5 (interleukin 5)
Diseases named in the same sentence as IL5 in open-access papers (continued):
Sharing a sentence is not in itself a finding about the gene and the disease.
airway hyperresponsiveness (continued). "CD86 siRNA treatment ameliorated OVA-induced airway eosinophilia, airway hyperresponsiveness, and the elevations of OVA-specific IgE in the sera and IL-5, IL-13, and CCL17 in the bronchoalveolar lavage fluid, but not the goblet cell hyperplasia." (PMID 25344652, 2014). "This was consistent with the report indicating that anti-IL-5 antibodies reduced BALF eosinophil counts but did not reduce BALF lymphocyte counts in a mouse model of OVA-induced airway-hyperresponsiveness." (PMID 40176907, 2025). "ILC2s are able to rapidly produce large amounts of type 2 cytokines and growth factors, such as IL-5, IL-13, and AREG to initiate type 2 immune responses, induce eosinophilic lung inflammation, airway hyperresponsiveness, mucus hypersecretion, and to drive healing and fibrotic repair." (PMID 39405112, 2024). "In same housed mice, ST2 deficiency reduced ozone-induced airway hyperresponsiveness and neutrophil recruitment in chow-fed but not HFD-fed mice even though ST2 deficiency reduced bronchoalveolar lavage IL-5 in both diet groups." (PMID 32326950, 2020). "Specifically, BLT1-null mice with OVA-induced bronchial asthma did not develop airway hyperresponsiveness or eosinophilic inflammation, and had reduced IgE production and decreased IL-5 and IL-13 in BAL fluid, suggesting an attenuated Th2-type response." (PMID 27669173, 2016). "Murine studies have shown that ILC2s are an early innate source of IL-5 and IL-13 after allergen exposure, which induce airway eosinophilic infiltration, mucus hyperproduction, and airway hyperresponsiveness but not allergen-specific IgE production." (PMID 26965110, 2016). "Therefore, through modulation of these TH2 cytokines, such as IL-5, IL-6, and IL-13, KWLL treatment was able to reduce eosinophils infiltration and airway hyperresponsiveness." (PMID 23533467, 2013). "The treatment of 18β-GA reduced IL-5, IL-13, TNF-α, OVA-specific IgE level and total IgE level while increased IFN-γ level, thereby helping to reduce the influx of leukocytes, goblet cell metaplasia, and airway hyperresponsiveness, as shown by lung histopathological analysis." (PMID 35210449, 2022). "LPS-reduced HDE challenge induced significantly higher concentrations of IFNγ, and IL-5 and IL-13 in the BAL fluid, but did not decrease airways hyperresponsiveness or airway resistance to methacholine challenge." (PMID 21345191, 2011). "Airway hyperresponsiveness as well as levels of IFN-γ, IL-13, IL-6, and IL-10 was lower in the lungs of asthmatic March1−/− mice compared to WT, whereas lung levels of TNF-α, IL-4, and IL-5 were not significantly different." (PMID 29854835, 2018).
helminth infection (109 papers, 2005 to 2025). "Worm-resistant domestic sheep have an upregulated IL-4 response when compared to susceptible sheep and similarly, IL-13 and IL-5, two other Th2-associated cytokines, have been negatively associated with worm infections in humans." (PMID 39963298, 2025). "ILC2s have been implicated in immune responses to extracellular helminth infections via the secretion of the type 2 cytokines IL-4, IL-5, IL-9 and IL-13." (PMID 40591723, 2025). "The cytokines were chosen based on the reduced treatment efficacy in ΔdblGata1 and IL-4r/IL-5−/− mice and to boost the type 2 immune response typically associated with helminth infections." (PMID 37440891, 2023). "Helminth infections, including Ascaris, have been linked to Th2 polarized immune responses with prominent IL-4 and IL-5 expression that typically contrasts with the Th1 immune responses associated with viral and bacterial infections." (PMID 37622109, 2023). "The immunological hallmark of helminth infections is their ability to induce Th-2 associated immune responses characterized by the presence of the IL-4, IL-5, IL-9, IL-10, and IL-13." (PMID 35087402, 2021). "Vitamin A deficiency (VAD) in mice leads to increased expression of IL-5, IL-13 and IL-4 by ILC2s in the small intestine upon helminth infection." (PMID 34759931, 2021). "Lastly, ILC2-derived IL-5 and IL-6 can regulate the production of antibodies by B lymphocytes in fat associated lymphoid clusters during helminth infection of the intestinal and lung barriers." (PMID 34759931, 2021). "In helminth infections, TCRγδ+ cells are associated, through the secretion of IL-4, IL-5 and IL-13, with the development of a Th2 response." (PMID 33023672, 2020). "Helminths infection elicited strong Th2 cell responses associated with significant productions of interleukin (IL)-4, IL-5, IL-9, IL-10, IL-13, IL-25, and IL-31." (PMID 32971770, 2020). "The previous research of defense mechanisms against helminths infections is typically associated with a type 2 immune response characterized by the expression of the cytokines IL-3, IL-4, IL-5, IL-9, IL- 10, and IL-13." (PMID 32243446, 2020). "Some previous studies have shown that Th2 immune responses associated with helminths infection were characterized by the induction of IL-4, IL-13, IgG, IgG1, and IgE antibodies in rats, and the generation of IL-3, IL-4, IL-5, and IL-13 in mice." (PMID 32971770, 2020). "Previously, it was noted that a type-2 immune response was responsible to helminth infections, which were usually associated with IL-10, IL-5 and IL-4 secretions." (PMID 32228657, 2020). "Helminth infections are typically associated with Type 2 cytokine responses with elevated levels of IL-4, IL-5 and IL-13." (PMID 30897083, 2019). "In whole blood cultures stimulated with A. lumbricoides antigen, the production of IL-5 was positively associated with increasing number of helminth infections." (PMID 25410903, 2014). "IL-5 regulates B-cell antibody production and enhances IgA production from B-cells, while IL-5 and IL-13 are implicated in allergic inflammation and protection against helminth infection." (PMID 35707544, 2022). "Alongside IL-5, elevated levels of IgE are a hallmark of helminth infection." (PMID 22509424, 2012). "Typically, chronic helminth infections are associated with the induction of a biased Th2associated immune response, although the response to schistosome parasites prior toegg-laying is thought to comprise a mixed Th1/Th2 phenotype with IFNγ productionalongside IL-4 and IL-5." (PMID 21445234, 2011). "Another theoretical concern for IL-4/13 and IL-5 blockers is helminth infections, since T2 immunity considerably protects against parasitic infections." (PMID 40843371, 2025). "The increased levels of IL-5 in rural children, in whom helminth infections are more frequent, reflects the importance of this cytokine in helminth response." (PMID 40943268, 2025).
helminth infection (continued). "In helminth infections, the immune response is predominantly skewed toward a Th2 profile, characterized by the activation of IL-4, IL-5, and IL-13 pathways, increased eosinophil recruitment, and IgE class-switching." (PMID 41227415, 2025). "In the gut, their classical role was attributed to protection against parasitic infections—a notion supported by the Th2-dominated responses (IL-4, IL-5, IL-13) and elevated eosinophil counts observed in helminthiasis." (PMID 40860650, 2025). "Conversely, Th2 cells and their signature cytokines (IL-4, IL-5, and IL-13) are largely characterized by their role in helminth infection or allergic responses and the promotion of IgE-mediated eosinophilic responses." (PMID 38672668, 2024). "During helminth infections, eosinophils support type 2 immunity by secreting IL-4, IL-5, IL-10, and IL-13." (PMID 39140728, 2024). "Helminth infection induced a Th2 response with elevated levels of IL-5 as well as parasite-specific IL-4, IL-5 and IL-13." (PMID 39204303, 2024). "In the present study, the Th2/anti-inflammatory cytokines, IL-4 and IL-5, were higher in the helminth infection and coinfection in vitro stimulations compared to the TB stimulation." (PMID 37513018, 2023). "Eosinophils are also known as the terminal effector cells during helminth infection; the most potent activator of which is the type 2 cell-produced cytokine- IL-5." (PMID 35500031, 2022). "In vivo blockade of IL-10 signalling during helminth infection resulted in an expansion of IFNγ+ and Tbet+ Th1 cells in the small intestine and a coincident decrease in IL-13, IL-5 and GATA3 expression by intestinal T cells." (PMID 35428872, 2022). "In mice where ILC2 are genetically ablated, IL-5 production by CD4+ T cells drops in MLN during helminth infection resulting in ablated expulsion of worm." (PMID 35145516, 2022). "iILC2 cells express more IL-25R and develop into nILC2-like cells, producing IL-5 and IL-13 after stimulation with IL-33 during worm infection." (PMID 35707544, 2022). "The type 2 cytokines IL-5 and IL-13 are also secreted early during a helminth infection by innate lymphocytes (ILC2) in response to the release of IL-33 and TSLP from mucosal epithelial sensor cells." (PMID 34083746, 2021). "Another neuropeptide, Calcitonin gene-related peptide (CGRP), suppresses IL-33- and NMU-activated ILC2s proliferation and IL-13 production but promotes IL-5 secretion during helminth infection." (PMID 34938670, 2021). "IL-4Rα signaling is crucial for the accumulation of GATA3+ Tregs in the inflamed intestine during helminth infections; therefore we analyzed the Th2 cytokines IL-4, IL-5, and IL-13 secreted by LPMCs in the colon." (PMID 34336843, 2021). "In this study, dendritic cells were suggested to be involved in the process of helminth infection-mediated modulation of allergic inflammation with a significant decrease in IL-4/IL-5 production and increased IL-10 production." (PMID 33692793, 2021). "Its activation in this tissue induces similar effects as those in the lung in terms of the induced expression of IL-5, IL-13, amphiregulin, CSF-1 and IL-9, leading to proliferation and promotion of a defense response against helminth infections." (PMID 34759931, 2021). "The immune environment in helminth infection is often characterized as T helper 2 (Th2) biased and involves the orchestration of cytokines (IL-4, IL-5, IL-13), antibodies, and regulatory cells." (PMID 33737927, 2021). "Basically, helminthic infection activates Th2 cells that secrete IL-4, IL-5 and IL-13, then IL-4 stimulates B cells to produce helminth-specific Ig-E, which opsonize the helminths and promote binding to IL-5 activated eosinophils via FcεR." (PMID 34413850, 2021). "In several helminth infections, IL-4, IL-13 and IL-5 producing Th2 cells are related to the most important effector mechanisms in adaptive pulmonary immunity against helminths." (PMID 34324507, 2021).
helminth infection (continued). "In the lung, IL-33 participates in the activation of most of the inflammatory processes in which ILC2s are involved; it does so by inducing the expression of IL-5 and IL-13, mainly in models of upper airway inflammation or helminth infection." (PMID 34759931, 2021). "Helminth infections usually trigger a Th2 immune response in the host, by releasing cytokines such as IL-4, IL-5, IL-13 and IL-33." (PMID 34324507, 2021). "The host showed mainly the Th2 type of immune response against helminth infection, characterized by the secretion of cytokines, such as IL-4, IL-5 and IL-13." (PMID 34930417, 2021). "Type 2 epithelial cytokines activate ILC2 and Th2 cells to produce IL-5 and IL-13, leading to eosinophil infiltration in allergic inflammation and helminth infection." (PMID 33335529, 2020). "In the context of helminth infection, IL-5 is known to be produced not only by CD4+ T cells but also type 2 innate lymphoid cells." (PMID 32571840, 2020). "Type 2 ILC (ILC2) are comparable to T helper 2 cells found in the adaptive immune system, which secrete cytokines such as interleukin 5 (IL‐5) and IL‐13 and have been found to play roles in host defense against helminth infections and in allergic responses." (PMID 31742928, 2020). "Basophils are granulocytes that produce type-2 cytokines including IL-4, IL-5, and IL-13 in addition to histamine, leukotrienes, and prostaglandins during degranulation as a result of helminth infection." (PMID 33193446, 2020). "Although IL-4, IL-5, and IL-13 are responsible for the majority of type-2 immune hallmarks observed during helminth infection, IL-9 has been described to have additional effects on worm clearance." (PMID 32793230, 2020). "Eosinophils play a pivotal role in fighting against some helminth infections, reflected by their dramatic increase in response to IL-5 produced by CD4+ type 2 helper T cells (Th2)." (PMID 33042162, 2020). "Elevated levels of IL-5 are related to the recruitment of eosinophils, neutrophils, and cells effective against helminth infections." (PMID 31765381, 2019). "Nonetheless, helminth infections or their products induce a type 2 immune response, which produces cytokines, such as IL‐4, IL‐5 and IL‐13." (PMID 31496071, 2019). "The IL-4, IL-5, IL-13, are cytokines typically associated with a T helper 2 (TH2) response, the predominant protective immune response against helminthic infections." (PMID 30870421, 2019). "ILC2s are present within visceral adipose tissue (VAT), where they are the predominant producers of IL-5 and IL-13 at homeostasis and following prolonged exposure to IL-33 or helminth infection." (PMID 30792718, 2019). "In general, helminth infections commonly induce a strong Th2 response, which is orchestrated by many different cell types and characterised, among others, by the secretion of IL-4, IL-5 and IL-13." (PMID 31315623, 2019). "Helminthic infections are uncommon in industrialized countries in the Northern hemisphere where anti-IL-5(R) antibodies have been administered so far." (PMID 29682504, 2018). "IL-9 functions as a central autocrine survival factor for ILC2 that initiate and amplify the adaptive type 2 immune response during helminth infection and allergic inflammation via production of IL-13 and IL-5, as demonstrated in C57BL/6 mice." (PMID 29872093, 2018). "Helminth infections are usually associated with Th2-type immune response characterized by the activation of CD4+ T helper cells and secretion of IL-4, IL-5, IL-9 and IL-13." (PMID 30189894, 2018). "Upon stimulation with IL-25, IL-33, or thymic stromal lymphopoietin (TSLP), ILC2 can produce IL-5, IL-13, and IL-4, similar to Th2 cells, which contribute to the control of helminth infection and pathology of allergic inflammation." (PMID 29354125, 2017). "During helminth infections, there is a predominant Th2 response characterized by a high production of IL-4, IL-5, IL-9, IL-10 and IL-13 cytokines." (PMID 27783986, 2016).
helminth infection (continued). "Although helminth-specific IgE, IL-5 and IFNγ responses were all decreased in fexofenadine treated mice, eosinophil numbers at the site of worm infection were significantly elevated." (PMID 26204515, 2015). "They expand strongly in vivo in response to IL-25 and IL-33, and represent the predominant early source of IL-5 and IL-13 during allergic inflammation and worm infection." (PMID 25659095, 2015). "Helminth infections, by their nature, lead to potent induction of Th2 responses (acutely) characterized by increased IL-4, IL-5, and IL-13 and—over time—to an expansion of Tregs." (PMID 24728010, 2014). "Even though they have common immunological features (elevated levels of IgE, eosinophilia, and production of Th2 cytokines such as IL-4 and IL-5), epidemiological studies revealed an inverse relationship between helminth infections and allergic diseases." (PMID 23844022, 2013). "Type 2 immune responses, characterized by the induction of cytokines IL-4, IL-5, the antibody isotypes IgG1 and IgE, as well as expanded populations of eosinophils, are induced by and confer protection against helminth infections in both humans and animals." (PMID 23844022, 2013). "Further, helminth infections induce the production of Th2 related cytokines, such as IL-4, IL-5, IL-9 and IL-13, with anti-inflammatory qualities." (PMID 23782752, 2013). "In chronic human and experimental infections, Schistosoma mansoni, like all helminth infections, induces a predominantly Th2 immune response, characterized by interleukin-4, IL-5, IL-9, IL-10 and IL-13, antibody (IgE and IgG4), eosinophils and mast cells." (PMID 23849678, 2013). "More specifically, helminth infections tend to promote a type 2 bias in the immune response, involving the production of the cytokines interleukin-4 (IL-4), IL-5, IL-10, and IL-13, as well as immunoglobulin E." (PMID 17083720, 2006). "Helminth infections are well known to induce Th2 and regulatory immune polarization, characterized by increased IL-4, IL-5, IL-10, and IL-13 production and expansion of T regulatory cells, which suppress Th1/Th17 effector responses critical for antimycobacterial immunity." (PMID 41583474, 2025). "In the context of helminth infections, Lck has also been identified as an immunomodulator of the immune system by promoting the T-helper-2 immune response characterized by the secretion IL-4, IL-5 and IL-13." (PMID 40725160, 2025). "Viewing an interaction conversely, we found several Th2 cytokines known to be highly expressed during helminth infection such as IL-4, IL-5, and IL-10 to also be influenced by concomitant diabetes (i.e., they had high DDI interaction term contributions of 42.79%, 36.51%, and 55.52% respectively)." (PMID 41174472, 2025). "Helminth infections typically induce modified type 2 immune responses, characterized by the release of effector cytokines interleukin (IL-) 4, IL-5, and IL-13 from Th2 cells and type 2 innate lymphoid cells (ILC), and by heightened production of anti-inflammatory IL-10 by regulatory T (Treg) cells." (PMID 39140728, 2024). "With regards to IL-5, a hallmark of helminth infections, CD4+ T cell responses in pre-patent and Mf-negative mice were comparable which strongly indicates that without developing microfilaremia, responses are dampened or Mf trigger T cell responses." (PMID 39436444, 2024). "All support the well-established type 2 hypothesis in helminth infections, marked by an increase in Th2 type cytokines such as IL-4, IL-5, and IL-13 in mucosal tissue of the bladder in response to Sh eggs as well as systemically and in lymphoid tissue." (PMID 39250522, 2024). "As a result, IL-5 and IL-13 levels can rise within hours of helminth infection." (PMID 36187827, 2022). "IL-5 is essential in the development and recruitment of eosinophils to sites of infection and stimulates the production of anti-microbial peptides and mucus in the intestinal epithelium during helminthiasis." (PMID 32450885, 2020).